PAFAH1B1 (platelet activating factor acetylhydrolase 1b regulatory subunit 1)
Description:
Regulatory subunit (beta subunit) of the cytosolic type I platelet-activating factor (PAF) acetylhydrolase (PAF-AH (I)), an enzyme that catalyzes the hydrolyze of the acetyl group at the sn-2 position of PAF and its analogs and participates in PAF inactivation. Regulates the PAF-AH (I) activity in a catalytic dimer composition-dependent manner (By similarity). Required for proper activation of Rho GTPases and actin polymerization at the leading edge of locomoting cerebellar neurons and postmigratory hippocampal neurons in response to calcium influx triggered via NMDA receptors (By similarity). Positively regulates the activity of the minus-end directed microtubule motor protein dynein. May enhance dynein-mediated microtubule sliding by targeting dynein to the microtubule plus end. Required for several dynein- and microtubule-dependent processes such as the maintenance of Golgi integrity, the peripheral transport of microtubule fragments and the coupling of the nucleus and centrosome. Required during brain development for the proliferation of neuronal precursors and the migration of newly formed neurons from the ventricular/subventricular zone toward the cortical plate. Neuronal migration involves a process called nucleokinesis, whereby migrating cells extend an anterior process into which the nucleus subsequently translocates. During nucleokinesis dynein at the nuclear surface may translocate the nucleus towards the centrosome by exerting force on centrosomal microtubules. May also play a role in other forms of cell locomotion including the migration of fibroblasts during wound healing. Required for dynein recruitment to microtubule plus ends and BICD2-bound cargos. May modulate the Reelin pathway through interaction of the PAF-AH (I) catalytic dimer with VLDLR (By similarity).
Synonyms: LIS1; MDCR; MDS; PAFAH; NudF; LIS2
Tractability: Small molecule: a structure with a bound ligand is known. PROTAC: ubiquitination databases record sites on it; its protein half-life has been measured.
Gene: Protein-coding gene on chromosome 17 (2,593,183 to 2,685,616, forward strand). Ensembl gene ENSG00000007168.
Subcellular location: Cytoplasm, cytoskeleton; Cytoplasm, cytoskeleton, microtubule organizing center, centrosome; Cytoplasm, cytoskeleton, spindle; Nucleus membrane
Subcellular location (Human Protein Atlas): Centrosome; Mid piece
Pathways (Reactome):
Cell Cycle: AURKA Activation by TPX2; Amplification of signal from unattached kinetochores via a MAD2 inhibitory signal; EML4 and NUDC in mitotic spindle formation; Loss of Nlp from mitotic centrosomes; Loss of proteins required for interphase microtubule organization from the centrosome; Mitotic Prometaphase; Recruitment of NuMA to mitotic centrosomes; Recruitment of mitotic centrosome proteins and complexes; Regulation of PLK1 Activity at G2/M Transition; Resolution of Sister Chromatid Cohesion; Separation of Sister Chromatids
Organelle biogenesis and maintenance: Anchoring of the basal body to the plasma membrane
Signal Transduction: RHO GTPases Activate Formins
Vesicle-mediated transport: COPI-independent Golgi-to-ER retrograde traffic
Gene Ontology:
Molecular function: dynein complex binding; protein binding; dynactin binding; heparin binding; identical protein binding; microtubule binding; phospholipase binding; phosphoprotein binding; protein heterodimerization activity; dynein intermediate chain binding; protein-containing complex binding
Biological process: adult locomotory behavior; brain morphogenesis; cerebral cortex development; corpus callosum morphogenesis; establishment of mitotic spindle orientation; microtubule organizing center organization; microtubule-based process; neuromuscular process controlling balance; neuron migration; acrosome assembly; actin cytoskeleton organization; chemical synaptic transmission; hippocampus development; layer formation in cerebral cortex; learning or memory; microtubule cytoskeleton organization; neuroblast proliferation; platelet activating factor catabolic process; platelet activating factor metabolic process; reelin-mediated signaling pathway; retrograde axonal transport; transmission of nerve impulse; vesicle transport along microtubule; auditory receptor cell development; cerebral cortex neuron differentiation; and 20 more
Cellular component: 1-alkyl-2-acetylglycerophosphocholine esterase complex; astral microtubule; cell cortex; centrosome; extracellular exosome; kinetochore; microtubule associated complex; nuclear envelope; cell leading edge; cytoplasm; cytosol; microtubule cytoskeleton; motile cilium; nucleus; perinuclear region of cytoplasm; axon; axon cytoplasm; central region of growth cone; cytoskeleton; glutamatergic synapse; growth cone; kinesin complex; neuronal cell body; nuclear membrane; Schaffer collateral - CA1 synapse; and 3 more
Genetic constraint (gnomAD): Loss-of-function variants: 0 observed, 29.73 expected, observed/expected ratio (o/e) 0, 90% interval 0 to 0.1. The upper end of that interval is the gene's LOEUF score, 0.1, which puts it in group 1 of 6, group 1 being the genes least tolerant of losing a copy. Missense variants: 165 observed, 357.05 expected, observed/expected ratio (o/e) 0.46, 90% interval 0.41 to 0.53. Synonymous variants: 109 observed, 121.99 expected, observed/expected ratio (o/e) 0.89, 90% interval 0.76 to 1.05.
Homologues: Orthologues: guinea pig PAFAH1B1 (99% identical), mouse Pafah1b1 (99% identical), pig PAFAH1B1 (99% identical), rat Pafah1b1 (99% identical), rabbit PAFAH1B1 (99% identical), dog PAFAH1B1 (99% identical), chimpanzee PAFAH1B1 (98% identical), macaque PAFAH1B1 (98% identical), tropical clawed frog pafah1b1 (95% identical), zebrafish pafah1b1a (94% identical), zebrafish pafah1b1b (94% identical), Drosophila melanogaster Lis-1 (70% identical), and 1 more. Paralogues in human: MAPKBP1 (24% identical), WDR62 (21% identical), TEP1 (20% identical), POC1A (20% identical), DAW1 (19% identical), POC1B (19% identical), WDR27 (19% identical), WDR5 (19% identical), WDR5B (18% identical), AHI1 (17% identical), SNRNP40 (16% identical), WDR7 (16% identical), and 14 more.
Diseases named in the same sentence as PAFAH1B1 in open-access papers:
PAFAH1B1 is named in the same sentence as 104 diseases in open-access papers, as found by Europe PMC text mining. Sharing a sentence is not in itself a finding about the gene and the disease. The quoted sentences say what the papers report.
Lissencephaly (152 papers, 2006 to 2026). A spectrum of malformations of cortical development caused by insufficient neuronal migration that subsumes the terms agyria, pachygyria and subcortical band heterotopia. "Heterozygous deletions or mutations of LIS1 (also known as PAFAH1B1) result in lissencephaly (smooth brain); biallelic mutations or deletions in NDE1 have been shown to result in microcephaly (small brain), microlissencephaly or microhydranencephaly." (PMID 38194050, 2024). "Although there are more than 31 lissencephaly‐related genes, up to 87% of patients with classic thick posterior to anterior gradient lissencephaly harbor causal variants in PAFAH1B1, the first gene identified in lissencephaly." (PMID 38129960, 2024). "A deep intronic deletion that caused abnormal splicing of the PAFAH1B1 gene was identified in a patient with classic lissencephaly." (PMID 38129960, 2024). "Biallelic variants in RELN encoding Reelin cause lissencephaly and hypoplasia or dysplasia of the cerebellum and hippocampus and heterozygous PAFAH1B1 variants are associated with lissencephaly." (PMID 39085459, 2024). "Here, we apply comprehensive genetic analysis to three children suspected to have monogenic DEE phenotypes and identify a novel and pathogenic de novo deep intronic 12 kb variant in PAFAH1B1 in a DEE due to classic lissencephaly." (PMID 38129960, 2024). "For instance, predominantly intrinsic mechanisms underlie lissencephaly caused by mutations in LIS1 (PAFAH1B1) or DCX." (PMID 35733184, 2022). "The currently oldest known individual with PAFAH1B1-associated lissencephaly lived to the age of 30 years." (PMID 38835877, 2022). "In isolated PAFAH1B1-associated lissencephaly, approximately 50 % live to the age of 10 years, and very few reach the age of 20 years." (PMID 38835877, 2022). "Case 1 identified a mutation in PAFAH1B1 (NM_000430:c.830A>C:p.His277Pro) and was diagnosed as Lissencephaly (LIS)." (PMID 33287870, 2020). "Lissencephaly (smooth brain) is a brain malformation disorder associated with haploinsufficiency of Lissencephaly-1 (LIS1), also called PAFAH1B1 (Platelet-activating factor acetylhydrolase IB subunit alpha)." (PMID 32159512, 2020). "Type I lissencephaly is a neuronal migration disorder caused by haploinsuffiency of the PAFAH1B1 (mouse: Pafah1b1) gene and is characterized by brain malformation, developmental delays, and epilepsy." (PMID 33150866, 2020). "Approximately 60% of patients with classical lissencephaly have been found to have deletions or mutations of PAFAH1B1, which playing a role in both cellular division and motility, as well as the regulation of brain levels of platelet activating factor." (PMID 33287870, 2020). "A final SNP, rs7219015, was found in an intron of PAFAH1B1 that, when mutated, leads to lissencephaly." (PMID 32134384, 2020). "There are no direct evidences for ASDs development and WDR37—however, recently, it has been demonstrated that WDR47 shares functional characteristics with PAFAH1B1, which causes lissencephaly." (PMID 31323926, 2019). "NudE/L bind directly to both dynein and the dynein co-factor Lis1 (also known in mammals as PAFAH1B1), mutations in which cause the brain development disease lissencephaly." (PMID 29192061, 2018). "Variations of PAFAH1B1 are linked to a posterior-to-anterior gradient of lissencephaly, while mutations of DCX are associated with an anterior-to-posterior gradient." (PMID 29628935, 2018). "MDC1093 had a diffuse SBH without cognitive delay and MDC1070 was a female with a mosaic mutation in PAFAH1B1 that led to SBH instead of lissencephaly." (PMID 28953922, 2017). "Hemizygous mutations in the human gene encoding platelet-activating factor acetylhydrolase IB subunit alpha (Pafah1b1), also called Lissencephaly-1, can cause classical lissencephaly, a severe malformation of cortical development." (PMID 28811646, 2017).
Lissencephaly (continued). "Mutations in the human gene PAFAH1B1 result in neuronal migration defects including lissencephaly, a smoothened cerebral cortex." (PMID 26834590, 2016). "The distal breakpoint was within an intron 1 of PAFAH1B1 (LIS1), a gene known to cause lissencephaly and the feature of IS." (PMID 24885232, 2014). "The gene encoding platelet-activating factor acetylhydrolase isoform 1b regulatory subunit 1 (PAFAH1B1, formerly LIS1) was initially identified as the causative gene of lissencephaly." (PMID 25053001, 2014). "In particular, deletion of PAFAH1B1 causes isolated lissencephaly while deletions involving both PAFAH1B1 and YWHAE cause Miller-Dieker syndrome." (PMID 23035971, 2012). "Heterozygous mutations of Pafah1b1 cause lissencephaly and a reduced number of cortical gyri, similar to the reeler phenotype." (PMID 21554715, 2011). "Heterozygous mutations in the PAFAH1B1 (LIS1) gene in humans causes a reduction in the number of cortical gyri (lissencephaly)." (PMID 17330141, 2007). "This individual with classic lissencephaly had a deep intronic variant in PAFAH1B1." (PMID 38129960, 2024). "Haploinsufficiency of PAFAH1B1 (encoding LIS1) causes an isolated lissencephaly sequence." (PMID 36544138, 2022). "PAFAH1B1 is considered to cause an isolated lissencephaly sequence and contribute to MDS." (PMID 36544138, 2022). "PAFAH1B1-associated lissencephaly/subcortical band heterotopia, also referred to as LIS1-associated lissencephaly/subcortical band heterotopia, encompasses Miller–Dieker syndrome (MDS), isolated lissencephaly sequence (ILS) and, infrequently, subcortical band heterotopia (SBH)." (PMID 31805691, 2019). "Interestingly, the SBH had a posterior predominance, as seen in PAFAH1B1 associated lissencephaly (see clinical report below)." (PMID 28953922, 2017). "Our findings provide evidence of a dramatic shift in excitability in the dentate gyrus of Pafah1b1+/− mice that may contribute to epilepsy or cognitive impairments associated with lissencephaly." (PMID 28811646, 2017). "Germline DCX mutations in males and PAFAH1B1 in either sex result in lissencephaly." (PMID 28953922, 2017). "In principle, any perturbation to cortical migration could lead to lissencephaly phenotypes, but most identified cases are attributed to mutations to LIS1 (also known as PAFAH1B1), doublecortin/DCX, and more recently TUBA1A." (PMID 29057214, 2017). "A single copy loss of PAFAH1B1 exon 1 and 2 was detected in one sample with lissencephaly." (PMID 28953922, 2017). "Miller-Dieker syndrome is characterized by severe lissencephaly caused by neuronal migration defects as well as craniofacial defects and is caused by a chromosomal deletion in the 17p13.3 region where the Lis1 (PAFAH1B1) and 14-3-3ε (YWHAE) genes are localized." (PMID 27001213, 2016). "These genes occur within the same 17p13.3 chromosomal region as the Lis1 gene (PAFAH1B1) that is frequently subject to microdeletion or microduplication events causative for the neurodevelopmental disorder Miller-Dieker Syndrome, in which patients exhibit severe lissencephaly." (PMID 36710926, 2022). "The psychomotor prognosis in LIS1/PAFAH1B1-related lissencephaly is significantly worse compared to DCX-related lissencephaly." (PMID 42177523, 2026). "Consistent with its function, haploinsufficiency of PAFAH1B1 is major responsible for lissencephaly phenotypes." (PMID 40390087, 2025). "Variants in PAFAH1B1/LIS1, DCX, and TUBA1A were recognized as key contributors to neuronal migration disorders, such as lissencephaly and subcortical band heterotopia, which frequently manifest with spasms in infancy." (PMID 41470225, 2025). "Our study found 18 out of 25 patients with PAFAH1B1 deletions or intragenic variations showed lissencephaly in their MRI tests, and the lissencephaly severity were independent of the extent of deletion." (PMID 40390087, 2025). "A novel de novo deep intronic 12 kb deletion in PAFAH1B1 was identified in the individual with lissencephaly." (PMID 38129960, 2024).
Lissencephaly (continued). "In comparison, another lissencephaly gene, Lis1 (Pafah1b1), was expressed at similar levels in all three cell types." (PMID 38194050, 2024). "Individuals with PAFAH1B1‐related lissencephaly typically have drug‐resistant seizures (often including infantile‐onset epileptic spasms), severe intellectual disability, and early mortality." (PMID 38129960, 2024). "In humans, mutations in LIS1 (PAFAH1B1; GeneID: 5048) or the dynein heavy chain gene (DYNC1H1; GeneID: 1778) cause the neurodevelopmental disease lissencephaly and other malformations of cortical development." (PMID 37620585, 2023). "For example, MV is found to be the most common prenatal ultrasound phenotype in MDS/PAFAH1B1-related lissencephaly." (PMID 37593446, 2023). "Pafah1b1, which was significantly downregulated in the IR + differentiation group, is a gene critical for brain development and is responsible for Lissencephaly." (PMID 36551187, 2022). "Platelet-activating factor acetylhydrolase 1B subunit 1 (PAFAH1B1) (also known as Lissencephaly-1 (LIS1)) contains an N-terminal Lish domain and seven WD40 repeats at the C-terminal." (PMID 36008729, 2022). "These observed abnormalities combine cortical findings characteristic of PAFAH1B1(LIS1)-related classic lissencephaly with wider brain findings more in keeping with the tubulinopathies." (PMID 36283405, 2022). "One known neuronal migration disorder is lissencephaly (LIS), which is caused by deletions or mutations of the LIS1 (PAFAH1B1) gene that has been implicated in regulating the microtubule motor protein cytoplasmic dynein." (PMID 35328531, 2022). "The lissencephaly phenotype is attributed to deletion of PAFAH1B1, formerly known as LIS1, while disruption of YWHAE, encoding 14–3-3ε, is associated with variable structure brain abnormalities, cognitive impairment and seizures." (PMID 35606653, 2022). "WDR47 (WD repeat-containing protein 47, MIM 615734), sharing structural homology with lissencephaly gene LIS1 (PAFAH1B1), participates in core microtubule-mediated processes, including neural stem cell proliferation, radial migration, and growth cone dynamics." (PMID 36277487, 2022). "In humans, mutations in both Lis1 (PAFAH1B1; hereafter called Lis1) and the dynein heavy chain (DYNC1H1) cause the neurodevelopmental disease lissencephaly." (PMID 34994688, 2022). "This revealed ~14,000 annotated ORFs and ~2500 uORFs, including a prominent uORF in the lissencephaly gene, Pafah1b1 or Lis1." (PMID 35762573, 2022). "Although the more severe neuronal migration phenotype displayed by MDS patients suggests that genes other than PAFAH1B1 are responsible for this phenotype, PAFAH1B1 is a major responsible gene for lissencephaly phenotypes seen in MDS patients." (PMID 35053800, 2021). "The implication of PAFAH1B1 in neuronal migration and Lissencephaly/MDS has been extensively analyzed and reported." (PMID 35053800, 2021). "Deletion or mutations of LIS1 (Lissencephaly 1 protein; encoded by PAFAH1B1, Platelet activating factor acetylhydrolase 1b regulatory subunit 1) are the major cause of classical lissencephaly in humans." (PMID 35069108, 2021). "Previous lissencephaly studies have demonstrated that migration of inhibitory interneurons is disrupted in Pafah1b1 heterozygous mutants." (PMID 33150866, 2020). "Classical lissencephaly can be modeled in mouse lines generated through heterozygous removal of Pafah1b1, which results in enlarged ventricles and disorganization of brain structures." (PMID 33150866, 2020). "Specifically, the PAFAH1B1/LIS1 and DCX genes, which are related to classical lissencephaly, appear to be associated to ISs in about 80% of affected children." (PMID 32827285, 2020). "Mice heterozygous for Pafah1b1 share symptoms with human lissencephaly patients, including learning deficits, motor impairments, increased excitability and decreased seizure threshold." (PMID 33150866, 2020).